AKT1 (AKT serine/threonine kinase 1)
Diseases named in the same sentence as AKT1 in open-access papers (continued):
Sharing a sentence is not in itself a finding about the gene and the disease.
breast cancer (continued). "Altogether, our findings from experimental models and the TCGA meta-analysis support the idea that tumor progression in breast cancer differentially involves AKT1 and AKT2 isoforms." (PMID 28287129, 2017). "Nine genes in this module – Akt1, Brca2, Ccnd1, Dnmt1, Mki67, Palb2, Rrm1, Timeless, and Top2a – are known human breast cancer genes according to the MalaCards database; four of them are hub genes." (PMID 28212608, 2017). "Conversely, expression of constitutively active AKT1 impairs breast cancer cell migration but promotes invasion of pancreatic carcinoma and fibrosarcoma cells." (PMID 28082369, 2017). "Using a minimum threshold of five mutated samples (test set) and focusing initially on breast cancer, we found that MMP2 predictions were strongly associated with predictions for PIK3CA (0.47), PTEN (0.49), and AKT1 (0.28), which operate via the same pathway." (PMID 29322935, 2017). "To measure the influence of AKT pathway in CCL19‐meditated breast cancer cells, we also used Akt1 siRNA." (PMID 28378417, 2017). "The IRS3 is a pseudogene in humans and IRS4 induces constitutive PI3K/AKT1 pathway hyperactivation in breast cancer cells." (PMID 28880250, 2017). "For metastatic breast cancer patients, it has been reported that the vast majority (>90%) of patients shed detectable levels of ctDNA into the blood circulation, indicating that plasma-based analysis could be a suitable approach for AKT1 E17K mutation detection in this patient population." (PMID 28472036, 2017). "Conversely, Akt1-KD has been reported to increase BRCA1 foci formation in MCF-7 breast cancer cells at 12 h after irradiation." (PMID 29156644, 2017). "Knockdown of AKT1 decreases cell migration in lung and ovarian cancer cells but increases cell migration in endometrial and breast cancer cells." (PMID 28082369, 2017). "Our results in breast cancer cell lines show that even though AKT1/AKT2 dual silencing reduces cell proliferation, it surprisingly enhances cell migration and invasion." (PMID 28287129, 2017). "The purpose of this study was to elucidate the mechanisms associated with the specific effects of AKT1 and AKT2 isoforms in breast cancer progression." (PMID 28287129, 2017). "In contrast, ErbB2-induced mammary tumors exhibited a higher invasive and metastatic potential in AKT1 knock-out mice." (PMID 28765579, 2017). "Although the pleiotropic effects of AKT1 in breast cancer have been reported, the genetic and epigenetic characteristics of AKT1 promoter region in breast cancer remains to be identified." (PMID 28301567, 2017). "It has been reported that activation of AKT1 contributes to resistance to anti-proliferative signals and breast cancer progression." (PMID 28301567, 2017). "These authors have reported an inhibitory effect of Akt1 overexpression on Rad51 foci formation and HR repair using an HR-reporter assay in normal tissue and breast cancer cells." (PMID 29156644, 2017). "In this study we aimed to investigate the promoter mutation spectrum, methylation and gene expression pattern of AKT1 and their relationship with breast cancer." (PMID 28301567, 2017). "In wild-type sporadic breast cancer lines, AKT1 has been shown to promote cytoplasmic retention of BRCA1 and Rad51." (PMID 27465688, 2016). "In a MMTV-ErbB2/Neu model of breast cancer, Akt1 ablation inhibited tumor formation, while Akt2 ablation enhanced mammary tumor growth." (PMID 27533079, 2016). "Expression of AKT1(E17K) has been shown to enhance cell migration and resistance to chemotherapeutic agents in luminal breast cancer cells." (PMID 27004402, 2016).
breast cancer (continued). "Akt1 has been shown to be an essential regulator of mammary cell differentiation in breast cancer via regulation of the STAT5 pathway." (PMID 27661110, 2016). "In this paper, Akt1 deletion contributed to decreased proliferation and increased apoptosis in mammary tumors, similar to what we observed in the ovarian tumors in the present study." (PMID 27533079, 2016). "Analysis of TCGA breast cancer data revealed that the mRNA expression, total protein levels, and phosphorylation of various RTKs are decreased in human tumors harboring AKT1(E17K)." (PMID 27004402, 2016). "This reflects the frequent activation of receptor tyrosine kinases, activating mutations in PI3KCA and AKT1, as well as overexpression of AKT2 or AKT3 and inactivation of the tumor suppressor gene PTEN in breast cancer." (PMID 26741489, 2016). "Many of the studies reporting increased invasiveness following Akt1 ablation were performed in breast cancer models, which rely on vascular metastasis." (PMID 27533079, 2016). "Blocking Akt1 in cancer cells suppressed the pro-survival effects of the COX-2+ TAMs on breast cancer cells." (PMID 26359357, 2015). "To assess the dependence of the stromal response on endocrine targeting tumor reduction in human breast cancer cell models, we employed T47D and IBH-6 cells expressing vector only (Acl4) or expressing an activated variant of Akt1 (myristoylated Akt1, myrAkt1)." (PMID 26098779, 2015). "In cancer cell migration and invasion, Akt1 and Akt2 appear to act antagonistically; thus, Akt1 suppresses, while Akt2 promotes, breast cancer cell migration and metastasis." (PMID 25575302, 2015). "Regarding metastases, different groups have reported that AKT1 down-regulation by short hairpin RNA in human breast cancer cell lines or its complete elimination by crossing MMTV-ErbB2 mice with Akt1 knockout animals leads to a higher rate of dissemination." (PMID 25853295, 2015). "These AKT isoforms seem to mediate different functions in cancer pathophysiology; for example, AKT1 appears to promote mammary tumor induction, whereas AKT2 promotes metastasis in previous reports." (PMID 26338103, 2015). "AKT1, KRAS and PIK3CA mutations and PTEN loss all exist in women with breast cancer in the mainland China." (PMID 25816324, 2015). "Abnormal activation of PI3K/AKT/mTOR (PAM) pathway, caused by PIK3CA mutation, KRAS mutation, PTEN loss, or AKT1 mutation, is one of the most frequent signaling abnormalities in breast carcinoma." (PMID 25816324, 2015). "In regards to breast cancer, studies have focused on the opposing functions of Akt1 and Akt2 on cell migration and invasion." (PMID 25069766, 2014). "Taken together, these data underline the importance of HR in protection against breast cancer and reveal the AKT1 signaling pathway as a missing link between hereditary and sporadic breast cancers." (PMID 24966870, 2014). "The serine-threonine kinase AKT1 plays essential roles during normal mammary gland development as well as the initiation and progression of breast cancer." (PMID 24628780, 2014). "Several studies have reported the hyperactivation of the oncogenic kinase AKT1 in 40-60% of sporadic breast cancers and in 40% of sporadic ovarian cancers." (PMID 24966870, 2014). "As demonstrated in this report, the majority of luminal- or basal-type mammary tumors showed an increased expression of AKT1 on the protein level and a significant upregulation of the Akt1m transcript." (PMID 24628780, 2014). "Studies in breast cancer and EC cells have identified contradictory effects of AKT1 and AKT2 on cancer cell motility." (PMID 25141911, 2014).
breast cancer (continued). "Future studies using Akt inhibitors for the treatment of breast cancer should employ Akt inhibitors that target both Akt1 and Akt2 in combination with inhibitors that target additional signaling pathways such as the MAPK signaling pathway." (PMID 23919516, 2013). "As indicated in these plots there was some variability regarding growth rates of mammary tumors in MTB-IGFIR/Akt1−/− and MTB-IGFIR/Akt2−/− mice, however, the majority of the tumors grew at a slower rate than the mammary tumors of MTB-IGFIR mice." (PMID 23919516, 2013). "Akt1 and Akt2 levels were stably ablated in mammary tumors of MTB-IGFIR transgenic mice by crossing MTB-IGFIR transgenic mice with either Akt1−/− or Akt2−/− mice." (PMID 23919516, 2013). "Despite the loss of Akt1 or Akt2, the mammary tumors from MTB-IGFIR/Akt1−/− and MTB-IGFIR/Akt2−/− mice had levels of phosphorylated Akt similar to the mammary tumors that developed in MTB-IGFIR mice." (PMID 23919516, 2013). "In MDA-MB-231 human breast cancer cells, which express low levels of activated Akt, the overexpression of constitutively active forms of Akt1 or Akt2 inhibited cell proliferation and migration with little effect on apoptosis." (PMID 23919516, 2013). "We have performed biochemical and functional characterization of six novel AKT1 pleckstrin homology domain mutants that have been identified predominantly in human breast cancers." (PMID 23237847, 2013). "The levels of Akt1 were undetectable in MTB-IGFIR/Akt1−/− mammary tumors while the levels of Akt2 were similar in MTB-IGFIR mammary tumors, and mammary tumors from MTB-IGFIR/Akt1−/− mice." (PMID 23919516, 2013). "Specific gain of function of Akt2 promotes migration and invasion in breast cancer epithelial cells, whereas Akt1 is mostly involved in cell proliferation and growth." (PMID 32309540, 2013). "The highest mutational frequency for all of the genes assessed in this study (PIK3CA and/or PIK3R1 and/or AKT1) was observed in HR+/ERBB2- tumors (133/289; 46.0%), while mutations were observed in up to 28% of cases in other breast cancer subtypes." (PMID 24229379, 2013). "AKT1 levels are higher in a panel of human breast carcinoma cell lines than in breast epithelial cells, particularly those with higher HER2 expression." (PMID 23437041, 2013). "The cytoplasmic retention of Brca1 and Rad51 also correlates with activated Akt1 in sporadic breast cancer tissues." (PMID 22481935, 2012). "Another recent study has shown that down-regulation of Akt1 enhanced epidermal growth factor (EGF)-stimulated cell migration in MCF-10A breast cancer cells." (PMID 22570727, 2012). "Some the RNAi target genes that are highly ranked by TARGETgene have been shown to play an important role in oncogenesis in each of the three cancer types, such as AKT1 (#1) in Breast Cancer." (PMID 22952662, 2012). "HER2-positive breast cancer cell lines and primary tumours were found to have high expressions of Akt1, Akt2 and their activated forms." (PMID 22842582, 2012). "A number of studies examined the role of Akt, especially the Akt1 and Akt2, in breast cancer and its prognostic and predictive value." (PMID 22842582, 2012). "In breast cancer cell lines with high level of Akt1 activity, IR-induced Brca1 and Rad51 foci formation and HRR are strongly impaired compared to cells with low Akt1 activity." (PMID 22481935, 2012). "Biopsies of sporadic breast cancer patients show strong correlation of Akt1 activation with cytoplasmic Brca1 and Rad51 localization." (PMID 22481935, 2012). "Increased cytoplasmic Skp2 expression correlated with p-Akt1 expression, with 54.2% (51/94) of low p-Akt1-expressing breast carcinomas, but 72.6% (114/157) of high p-Akt1-expressing breast carcinomas exhibiting cytoplasmic Skp2 expression." (PMID 23300741, 2012).
breast cancer (continued). "To investigate the role of cytoplasmic Skp2 expression in human breast carcinomas, we immnohistochemically assessed cytoplasmic Skp2, p-Akt1, and p27 expression in 251 patients with invasive ductal carcinomas of the breast." (PMID 23300741, 2012). "Akt1 and Akt2 were expressed in all tested breast cancer cell lines, but Akt3 was detectable only in MDA-MB-231 cells." (PMID 21362200, 2011). "An advantage of our study is that all the cells had the same genetic background as they all were MCF-7 breast cancer cells, however they differed in the levels of activated Akt-1 expression due to introduction of an activated Akt-1 gene." (PMID 21730367, 2011). "Recent studies have established links between DDR and the oncogenic kinase AKT1, which is upregulated in about 50% of sporadic breast cancers." (PMID 21321378, 2010). "More specifically, the activation of AKT1 shows a deficient phenotype in BRCA1 and HR, revealing molecular similarities between hereditary and sporadic breast cancers." (PMID 21321378, 2010). "The inhibition of HR by AKT1 is mechanistically consistent with its role in breast cancer, i.e., under pathological conditions." (PMID 21321378, 2010). "Activating somatic mutations of other oncogenes (EGFR, KRAS, HRAS, NRAF, BRAF and AKT1) involved in downstream molecular events following tyrosine kinase receptor activation are frequent in several malignancies but rare in breast cancer." (PMID 21209903, 2010). "This sequestration of BRCA1 and RAD51 to the cytoplasm has been observed both in cultured cell lines and in 60% of sporadic breast cancer tumors, in which it is correlated with the level of AKT1 activation." (PMID 21321378, 2010). "Since EF1α is often overexpressed in breast cancer, the consequences of EF1α increased levels for proliferation, survival and invasion will likely depend on the relative concentration of Akt1 and Akt2." (PMID 19646290, 2009). "The bitransgenic MMTV-c-ErbB2, MMTV-myr-Akt1 mice developed single focal mammary tumours with a mean latency of 114 days, meaning the bitransgenic animals develop mammary tumours twice as fast as the MMTV-c-ErbB2 mice." (PMID 18700973, 2008). "Breast cancer patients with high-grade tumors and late stage of diagnosis had activated Akt1 in their tumor cells and their disease had a poor outcome." (PMID 18184439, 2008). "Akt1 is overexpressed in breast cancer cells and has been shown to be important in estrogen-stimulated growth." (PMID 19430575, 2008). "Altogether, 57 AKT1-signature genes had p-values less than 0.01 in three breast cancer data sets, from which 34 genes were regarded as RAD001-insensitive and 23 genes as RAD001-sensitive." (PMID 18652687, 2008). "Bitransgenic MMTV-c-ErbB2, MMTV-myr-Akt1 mice develop mammary tumours twice as fast as MMTV-c-ErbB2 mice." (PMID 18700973, 2008). "Its activity is controlled in part by Phosphatylinositol-3-Kinase (PI3K)/Akt1 signaling, and disruption of this regulatory connection has been identified in human breast cancers." (PMID 16780593, 2006). "For example, in breast cancer cells expression of constitutively active Akt1 reduced the ability of doxorubicin or ionizing radiation to induce apoptosis." (PMID 16168126, 2005). "Akt-1 has been found in correlation with higher expression of erbB-2 in a panel of breast cancer cell lines." (PMID 11870534, 2002). "However, Pipp ablation in the MMTV-PyMT oncogene-driven murine mammary cancer model enhances AKT activation and tumor growth, but paradoxically reduces lung metastasis via AKT1 activation." (PMID 41408399, 2025).
breast cancer (continued). "The PAM pathway is the most commonly activated signaling pathway in breast cancer, which may result from activating mutations in the PIK3CA and AKT1 genes or inactivating alterations in the PTEN gene." (PMID 40206206, 2025). "Further, we detected AKT1 phosphorylation in breast cancer tissues by immunostaining." (PMID 40135844, 2025). "Additionally, PIK3CA and AKT1 mutations, as well as the loss of PTEN, contribute to the estrogen‐independent growth of breast cancer cells." (PMID 40206206, 2025). "Conversely, AKT1 is overactivated in breast cancer, leading to increased mammary tumor growth." (PMID 39482666, 2024). "AKT1 genetic alterations were reported in some cancers, including breast cancer." (PMID 39329938, 2024). "Dysregulation of the PI3K/AKT/mTOR pathway by activating mutations in PIK3CA and AKT1 and/or inactivating PTEN are most frequently observed in HR+/HER2- BCs, which are found to be mutually exclusive (GENIE breast cancer cohort)." (PMID 39796647, 2024). "Consequently, capivasertib has become the first FDA-approved AKT inhibitor for use in HR-positive and HER2-negative breast cancer patients with one or more PIK3CA/AKT1/PTEN alterations." (PMID 38791529, 2024). "Further research indicated that CXCR2 could promote breast cancer chemoresistance by inhibiting AKT1 signaling and activating COX2 signaling." (PMID 39394189, 2024). "In a Chinese breast cancer cohort, researchers found that most of the missense mutations were AKT1 E17K mutations, a finding not observed in the TCGA cohort." (PMID 39769140, 2024). "A phase 2 trial (plasma MATCH trial) of treatment selection with ctDNA mutations in breast cancer showed the efficacy of neratinib for ERBB2 mutations and capivasertib for AKT1 mutations in ctDNA, indicating the usefulness of examining genetic mutations in ctDNA." (PMID 38539518, 2024). "Furthermore, AKT1 is also reported to inhibit breast cancer cell migration, by regulating EMT proteins promote local tumour growth, and critically implicated in proliferation in TNBC." (PMID 39281650, 2024). "Desmedt and colleagues identified alterations in one of three key genes of the PI3K pathway: PIK3CA, PTEN, and AKT1, in 50% of ILC breast cancer cases, each more frequently mutated in ER-positive/HER2-negative ILC breast cancer than in ER-positive/HER2-negative invasive ductal breast cancer tumours." (PMID 38534931, 2024). "Taken together, these results suggest that AKT1 is a crucial regulator of STING signaling in endocrine‐resistant breast cancer cells and that knockdown of AKT1 or targeting AKT1 by MK2206 could release the activity of STING signaling." (PMID 39023171, 2024). "However, context and cell-type specific effects have to be considered, as seen for example for Akt1, which is pro-migratory in untransformed fibroblasts but anti-migratory in breast cancer cells, or for Akt2 showing the opposite effects in these cell types." (PMID 38291468, 2024). "We further confirmed whether targeting AKT1 could reverse the activity of the cGAS‐STING pathway in endocrine‐resistant breast cancer cells." (PMID 39023171, 2024). "For contemporary breast cancer actionability, PIK3CA mutation is a biomarker for the FDA-approved PI3Kα inhibitor alpelisib, AKT1 mutation is indicated for agents such as capivasertib (AZD5363) and ipatasertib, and ERBB2 mutation for tyrosine kinase inhibitor neratinib." (PMID 37760445, 2023). "A second AKT1 inhibitor in development, ipatasertib, is currently undergoing phase I evaluation with maintenance pertuzumab and trastuzumab in patients with HER2-positive advanced breast cancer harbouring PIK3CA mutations (NCT04253561)." (PMID 38201451, 2023).